MAFB (MAF bZIP transcription factor B)
Diseases named in the same sentence as MAFB in open-access papers (continued):
Sharing a sentence is not in itself a finding about the gene and the disease.
scoliosis (2 papers, 2022 to 2023). A congenital or acquired spinal deformity characterized by lateral curvature of the spine. "In addition, upregulation of ERC2 and MAFB gene expression in AIS patients may promote hypertrophy of the ligamentum flavum to adapt to mechanical stresses generated by scoliosis via the TGF-β pathway." (PMID 38322243, 2023).
Alzheimer disease (1 paper, 2022). A progressive, neurodegenerative disease characterized by loss of function and death of nerve cells in several areas of the brain leading to loss of cognitive function such as memory and language. "The expression of transcription factors in each module had a substantial positive connection, and FOSL1, HES4, and MAFB identified the genes in the M4 module as a possible cluster of transcriptional regulators linked to the start of Alzheimer’s disease." (PMID 35592698, 2022).
aneurysm (1 paper, 2017). Bulging or ballooning in an area of an artery secondary to arterial wall weakening. "Consistently, disease ontology terms for human vasculature diseases, such as aneurysm, retinal vascular disease, diabetic retinopathy and diabetic angiopathy, and carotid artery disease were also significantly enriched in MafB peak-associated genes." (PMID 28959057, 2017).
aphakia (1 paper, 2024). "We found that transcription factors implicated in vertebrate lens development (Prox1a, MafB, c-Maf, FoxE3) failed to initiate expression in the presumptive lens tissue of Pax6.1 mutant fish resulting in aphakia, a phenotype observed previously in Pax6 mutant mice." (PMID 39512904, 2024).
B-cell CLL/ (1 paper, 2009).
Bardet-Biedl syndrome (1 paper, 2021). A ciliopathy with multisystem involvement. "For example, HES2, MAFB, RPS12, RPL12, RPS15, and AFF2 are all associated with cancer, whereas BBS12 is a gene related to Bardet-Biedl Syndrome, a multi-organ genetic disease that can involve hypoplasia of the uterus, ovaries, and fallopian tubes." (PMID 34215221, 2021).
chronic hepatitis C (1 paper, 2019). "In the present study, elevated MafB negatively correlated with reduced serum IFN-α1 level in chronic hepatitis C patients." (PMID 31447817, 2019). "MafB mRNA was approximate 5-flod elevation in PBMCs from chronic hepatitis C patients than those from healthy individuals (Student’s t test, p < 0.0001)." (PMID 31447817, 2019). "Inhibition of MafB in CD14+ monocytes purified from chronic hepatitis C patients induced elevated IFN-α1 secretion, which was accompanied by IRF3 phosphorylation." (PMID 31447817, 2019). "MafB protein expression in PBMCs was also remarkably increased in chronic hepatitis C patients with approximately 10-fold elevation when compared with healthy individuals (Student’s t test, p < 0.0001)." (PMID 31447817, 2019). "By contrast, MafB was notably elevated in chronic hepatitis C patients and negatively correlated with serum IFN-α1." (PMID 31447817, 2019). "The current data revealed that overexpression of MafB in chronic hepatitis C patients might suppress type I IFN production by CD14+ monocytes, leading to the viral persistence." (PMID 31447817, 2019). "MafB might be a potential therapeutic target for treatment of chronic hepatitis C." (PMID 31447817, 2019). "Interestingly, both MafB mRNA and protein level were negatively correlated with serum IFN-α1 expression in chronic hepatitis C patients (Spearman correlation analyses, r = −0.412, p = 0.026 and r = −0.472, p = 0.0097, respectively)." (PMID 31447817, 2019). "However, MafB inhibition did not affect CD14+ monocytes-induced CD4+ T cells differentiation in vitro in chronic hepatitis C patients." (PMID 31447817, 2019). "However, there were no remarkable correlations between MafB level (either mRNA or protein) and IFN-β expression in chronic hepatitis C patients (Pearson correlation analyses, p > 0.05)." (PMID 31447817, 2019). "Importantly, MafB inhibition directly promoted IFN-α1 production, but not IFN-β, by CD14+ monocytes from chronic hepatitis C patients, which was accompanied by IRF3 phosphorylation." (PMID 31447817, 2019).
chronic viral hepatitis (1 paper, 2019). "However, the role of MafB in modulation of CD14+ monocytes in chronic viral hepatitis was not fully elucidated." (PMID 31447817, 2019).
cleft lip (1 paper, 2015). Congenital defect in the upper lip where the maxillary prominence fails to merge with the merged medial nasal prominences. "In addition to IRF6, v-maf musculoaponeurotic fibrosarcoma oncogene homolog B (MAFB) and intron 6 of the ATP-binding cassette subfamily A member 4 (ABCA4) also contribute to the risk of cleft lip and palate." (PMID 26322076, 2015).
colitis (1 paper, 2024). Inflammation of the colon. "We also demonstrated that the upregulation of MAFB inactivated NF‐κB pathway in DSS‐caused colitis mice." (PMID 39172054, 2024). "We observed that MAFB was lowly expressed in dextran sulfate sodium (DSS)‐caused colitis mice." (PMID 39172054, 2024). "Our study observed that MAFB expression was downregulated in DSS‐caused colitis mice." (PMID 39172054, 2024). "Together, these data suggested that the upregulation of MAFB could protect mice from DSS‐caused colitis." (PMID 39172054, 2024). "Collectively, these results indicated that MAFB level was downregulated in DSS‐induced colitis of mice." (PMID 39172054, 2024). "To define the relevance between MAFB and UC, we examined MAFB level in DSS‐induced colitis in C57BL/6J mice." (PMID 39172054, 2024). "The reduced levels of Occludin and ZO‐1 caused by DSS were markedly reversed after the treatment of MAFB overexpression, proving that the upregulation of MAFB could inhibit DSS‐induced intestinal barrier impairment in colitis mice." (PMID 39172054, 2024). "Moreover, the upregulation of MAFB protected mice from DSS‐induced colitis by suppressing DSS‐induced inflammation, oxidative stress, and intestinal barrier impairment." (PMID 39172054, 2024). "Moreover, immunohistochemistry staining results demonstrated that MAFB protein expression was significantly downregulated in colonic epithelia of DSS‐induced colitis mice." (PMID 39172054, 2024). "In addition, qRT‐PCR also demonstrated that the mRNA level of MAFB was markedly reduced in DSS‐induced colitis of mice." (PMID 39172054, 2024). "In summary, we first observed that MAFB expression was downregulated in DSS‐induced colitis mice." (PMID 39172054, 2024). "Our findings also verified that MAFB upregulation could suppress inflammation and oxidative stress in DSS‐treated colitis mice and in LPS‐treated IEC‐6 cells." (PMID 39172054, 2024). "Overall, these results demonstrated that the upregulation of MAFB could suppress DSS‐induced inflammation and oxidative stress in colitis mice." (PMID 39172054, 2024). "However, the function of MAFB in colitis has not been evaluated till date." (PMID 39172054, 2024).
colon cancer (1 paper, 2024). "MAFB and CTHRC1 showed significant gene amplification in colon cancer tissues." (PMID 38577604, 2024). "Notably, SPINK1 and CXCL11 gene copy numbers exhibited a positive correlation with gene mRNA levels, while MAFB copy number displayed a negative correlation with its gene mRNA level in colon cancer tissues." (PMID 38577604, 2024).
Dengue virus infection (1 paper, 2019). "Dysregulation of MafB was found in Zika and Dengue virus infection." (PMID 31447817, 2019).
diphtheria (1 paper, 2024). A Gram-positive bacterial infection caused by Corynebacterium diphtheriae. "A scRNA-seq study in mice in which tissue resident IMs were depleted with diphtheria, identified MafB as the transcription factor restricting monocyte proliferation and promoting their differentiation toward tissue-resident IMs." (PMID 39613751, 2024).
glomerular disease (1 paper, 2023). "Many of the transcription factors have previously been shown to play a role in podocyte injury and glomerular disease, such as MAFB, TCF21, DACH1 and the recently reported FOXC1." (PMID 37681897, 2023).
Hydrocephalus (1 paper, 2023). Hydrocephalus is an active distension of the ventricular system of the brain resulting from inadequate passage of CSF from its point of production within the cerebral ventricles to its point of absorption into the systemic circulation. "Importantly, the mechanism of RARα on hydrocephalus was associated with MAFB, MSR1, and neuroinflammation." (PMID 36768908, 2023). "In conclusion, activation of the RARα attenuated CSF hypersecretion to inhibit hydrocephalus development via regulating the MAFB/MSR1 pathway." (PMID 36768908, 2023). "Taken together, the current outcomes demonstrated that activation of the RARα attenuated CSF hypersecretion to inhibit hydrocephalus development, at least in part through the MAFB/MSR1 pathway." (PMID 36768908, 2023). "Therefore, we postulated that RARα receptor stimulation decreased CSF secretion via regulating inflammation in hydrocephalus by promoting the MAFB/MSR1 pathway." (PMID 36768908, 2023).
Immunodeficiency (1 paper, 2020). Failure of the immune system to protect the body adequately from infection, due to the absence or insufficiency of some component process or substance. "To further investigate the functional consequences of MAFB loss, we transplanted MAFB+/+ and −/− PP and β-like cell stages under the kidney capsules of immunocompromised NOD SCID (severe combined immunodeficiency) beige mice (Jackson Laboratories)." (PMID 32488111, 2020).
intervertebral disc degeneration (1 paper, 2024). "The genes that are upregulated in the IVDD group, such as JUNB, SYDE1, ADAM8, and MAFB, are primarily involved in inflammatory responses, extracellular matrix remodeling, and cellular stress responses, which are processes known to be associated with intervertebral disc degeneration." (PMID 39430414, 2024).
lentivirus infection (1 paper, 2016). Virus diseases caused by the Lentivirus genus. "MAFB shRNA678 plasmid contains mCherry protein expression cassette and lentivirus infection efficiency could be assessed from the pink color of the tumor, and retrovirus infection efficiency was determined via western blotting." (PMID 27829226, 2016).
Lewis lung carcinoma (1 paper, 2020). "MafB+ macrophages expressed high levels of IL-10, ARG1 and TNF-α in Lewis lung carcinoma (LLC) of MafB-GFP knock-in heterozygous mice." (PMID 32486098, 2020).
lymph node metastasis (1 paper, 2022). "Our results indicated that higher numbers of MAFB+ cells significantly correlated to increased local lymph node metastasis (nodal involvement), high recurrence rate, poor pathological stage, increased lymphatic permeation, higher vascular invasion, and pleural infiltration." (PMID 36077342, 2022).
malaria (1 paper, 2013). Malaria is a serious and sometimes fatal disease caused by a parasite that commonly infects a certain type of mosquito which feeds on humans. "A macrophage differentiation inducer, MafB, is up-regulated after malaria." (PMID 24188121, 2013).
malignant osteopetrosis (1 paper, 2021). "The defects we observe in the Csf1rko rats resemble skeletal dysplasia caused by mutations in the gene encoding the macrophage-enriched transcription factor MAFB and more generally various forms of malignant osteopetrosis." (PMID 34081701, 2021).
multiple sclerosis (1 paper, 2021). A progressive autoimmune disorder affecting the central nervous system resulting in demyelination. "MAFB (FC = 1.29, p = 0.03) is a transcriptional regulator of mature microglia which is upregulated during multiple sclerosis disease progression and found to inhibit apoptosis of macrophages." (PMID 33964983, 2021).
neuroblastoma (1 paper, 2020). Neuroblastoma (NB) is the most common solid, extracranial childhood tumor. "Notch pathway targets and effectors were highly induced in our RNA-seq of IMR32 treated with BMP4, so we first validated a panel of Notch pathway genes, including HES1, MAFB, MAML2 and NOTCH3, confirming a BMP4-Notch signaling pathway in neuroblastoma." (PMID 32210188, 2020).
pneumonia (1 paper, 2024). An acute, acute and chronic, or chronic inflammation focally or diffusely affecting the lung parenchyma, caused by an infection in one or both of the lungs (by bacteria, viruses, fungi, or mycoplasma.). "SCENIC analyses predicted higher MAF and MAFB activities in the Mo-Mac cluster compared to other clusters, further supporting that the airspace of human pneumonia lungs contains Mo-Macs that are transcriptionally similar to mouse Ly6G+ Macs." (PMID 39093958, 2024).
pulmonary diseases (1 paper, 2017). "In the other hand, the -613C>T change, present only in the TCCT haplotype, caused the appearance of putative binding sites for SOX15 and for MAFB, which have been associated to pulmonary diseases." (PMID 29088248, 2017).
renal fibrosis (1 paper, 2024). A final common manifestation of a wide variety of chronic kidney diseases characterized by glomerulosclerosis and tubulointerstitial fibrosis. "Moreover, TCF4 and MAFB, which are highly enriched in ECM_FIB, are associated with renal fibrosis and epithelial–mesenchymal transition, respectively." (PMID 38982264, 2024).
T-cell leukemia (1 paper, 2019). A malignant disease of the T-lymphocytes in the bone marrow, thymus, and/or blood. "Human T-cell leukemia virus basic leucine-zipper factor abrogated DNA-binding activity and reduced the steady-state levels of MafB, leading to the disruption of transcriptional control of cellular genes and induction of adult T-cell leukemia." (PMID 31447817, 2019).
ulcerative colitis (1 paper, 2024). An inflammatory bowel disease involving the mucosal surface of the large intestine and rectum. "The upregulation of MAFB protects against ulcerative colitis via the suppression of inflammation, oxidative stress and the intestinal barrier impairment through inhibiting the NF‐κB pathway." (PMID 39172054, 2024). "The aim of this study was to explore whether MAF bZIP transcription factor B (MAFB) might alleviate ulcerative colitis (UC) in dextran sulfate sodium (DSS)‐induced mice and LPS‐induced IEC‐6 cells." (PMID 39172054, 2024).
Wilms tumor (1 paper, 2023). An embryonal neoplasm characterized by the presence of epithelial, mesenchymal, and blastema components. "Nevertheless, to our knowledge, our findings provide the first evidence of the podocyte lineage markers MAFB and PODXL at protein level in Wilms tumor." (PMID 37815464, 2023). "Expression of MAFB and PODXL has been reported in Wilms tumor cell lines and expression of PODXL has been observed in prior microarray analyses of Wilms tumors of varying histology." (PMID 37815464, 2023).
ZIKV infection (1 paper, 2018). "Genes associated with cell differentiation and proliferation, such as BUB1, DLGAP5, PBK and CEP55 (Cluster 3) were upregulated during DENV infection but not ZIKV, while EGR1, HBEGF and MAFB (Cluster 4), were up-regulated at d17 POS during ZIKV infection." (PMID 30596671, 2018).
tumor (35 papers, 2004 to 2025). "Here we found that they also exhibit higher phosphorylation levels of several kinases and TFs, which were previously associated with macrophages that promote tumor growth, such as MAFB, HSF1, PKACα, and PDPK1." (PMID 41255709, 2025). "Disruption of the transcription factors MafB and c-Maf in KCs by this approach can overcome tumor-induced KC loss and dysfunction and elicit unprecedented therapeutic effects against various types of metastatic liver cancer." (PMID 36821387, 2023). "We have previously identified MAFB as a candidate marker for tumor-associated macrophages (TAMs) in human and mouse models." (PMID 36077342, 2022). "A report showed that the expression of MAFB oncoprotein is regulated by the cytolethal distending toxin of enterohepatic HP, and MAFB is specifically expressed in tumour-associated macrophages to induce angiogenesis." (PMID 36248367, 2022). "Targeted disruption of MafB and c-Maf expression using this approach could overcome tumor-induced KC loss and dysfunction, eliciting unprecedented therapeutic effects against various types of metastatic liver cancer in mice." (PMID 36821387, 2023). "Notably, E. coli–sgMafb/Maf injection did not amplify KCs in tumor-free naive mice, indicating the involvement of tumor-derived factors in driving the proliferation of MafB/c-Maf–deficient KCs." (PMID 36821387, 2023). "In addition, GPR68 is associated with tumor suppressor and MAFB is associated with proto-oncogene and tumor suppressor activities." (PMID 34715892, 2021). "Liver-resident Kupffer cells showed progressive loss of the core transcription factors SPIC and MAFB, suggesting a potential transition into SPP1+ TAMs under tumor pressure." (PMID 40725473, 2025). "SPIC and MAFB were predominantly expressed in normal and adjacent tissues, while SPP1+ TAM-associated TFs (SREBF1, JUN, SPI1, and CREB1) showed peak expression in tumor core regions." (PMID 40725473, 2025). "To validate our findings, we employed Kaplan-Meier survival curves and ROC curves to analyze the key genes associated with C2 tumor cell subtypes, including the top five transcription factors (IGF2, PRRX1, MAFB, LBX2, GATA2, MAFG)." (PMID 39896800, 2024). "MAFB activity was consistently decreased in the R vs. the NR groups across various tumor-infiltrating immune cell categories, including Macro/Mono, DC, and Mast categories." (PMID 39034339, 2024). "While whole-cell engulfment was rarely observed, DKO macrophages were frequently found to grab small cell fragments from the body of intimately interacting tumor cells, resembling the tumor-nibbling behavior of MafB/Maf-edited KCs in vivo." (PMID 36821387, 2023). "Tumor tissues from these patients were extracted and stained with anti-human MAFB antibody, and then MAFB-positive cells relative to the tissue area (MAFB+ cells/tissue area) were morphometrically quantified." (PMID 36077342, 2022). "Our animal assay manifested that decreased circ_0051079 repressed tumor growth by modulating miR-1286 and MAFB levels." (PMID 36153605, 2022). "C1Q Macros expressed C1QA/B/C genes similarly to MAFB+ LC, but uniquely expressed FCGR3A and were enriched in a C1Q tumor-associated macrophage (TAM) gene-set." (PMID 36741389, 2022). "Overtime, some functional (e.g., M-CSF and GM-CSF) and transcriptional (e.g., IRF4 and MAFB) factors in the TME induce monocyte differentiation into pro-tumoral, tumor-associated macrophages and dendritic cells, which help tumor cells avoid cytotoxic T cells." (PMID 33968780, 2021). "We identified MAFB amplifications in a majority of tumor types in an assessment of The Cancer Genome Atlas database." (PMID 27829226, 2016). "Immunohistochemical staining showed that MAFB protein levels were also increased in CRC tissues as compared to adjacent non-tumor tissues (Figure 1Ca –1Cd)." (PMID 27829226, 2016). "We studied the status of MAFB in TCGA and found aberrant MAFB amplification in a majority of enrolled tumor types." (PMID 27829226, 2016).